AMHR2 (anti-Mullerian hormone receptor type 2)
Diseases named in the same sentence as AMHR2 in open-access papers (continued):
Sharing a sentence is not in itself a finding about the gene and the disease.
autoimmune oophoritis (1 paper, 2015). Autoimmune oophoritis is a rare cause of primary ovarian insufficiency (POI). "We found that AMHR2-CD immunization of C57BL/6 females induced a prominent antigen-specific proinflammatory CD4+ T cell response that resulted in a mild transient autoimmune oophoritis that resolved rapidly with no detectable lingering adverse effects on ovarian function." (PMID 26618181, 2015).
colorectal cancer (1 paper, 2024). A primary or metastatic malignant neoplasm that affects the colon or rectum. "Recently, AMHR2 expression in nongynecological cancers has been demonstrated in a large panel of tumor samples, showing that AMHR2 is expressed in the plasma membrane in more than 50% of the renal cell carcinomas, hepatocellular carcinomas, colorectal cancers, and NSCLC samples analyzed." (PMID 39230026, 2024).
congenital hypogonadotropic hypogonadism (1 paper, 2019). Congenital hypogonadotropic hypogonadism (CHH) is a rare disorder of sexual maturation characterized by gonadotropin (Gn) deficiency with low sex steroid levels associated with low levels of follicle stimulating hormone (FSH) and luteinizing hormone (LH). "Summary of heterozygous AMH or AMHR2 mutations identified in patients with congenital hypogonadotropic hypogonadism." (PMID 31291191, 2019).
germ cell tumor (1 paper, 2020). A benign or malignant, gonadal or extragonadal neoplasm that originates from germ cells. "Similar patterns were preserved in almost all conditions; however, in nonseminomatous germ cell tumors the tissue architecture was lost, including AMHR-2 expression." (PMID 32026338, 2020).
infiltrating urothelial bladder carcinoma (1 paper, 2020). "GLI1 showed a significant level of co-expression in mucinous breast carcinoma and ovarian serous surface papillary carcinoma, whereas AMHR2, CHRD, and ACVR2A showed a similar pattern in ovarian serous papillary carcinoma, superficial bladder carcinoma and infiltrating urothelial bladder carcinoma." (PMID 31973134, 2020).
intestinal polyp (1 paper, 2011). Discrete abnormal tissue masses that protrude into the lumen of the intestine. "Dysregulated Wnt/β-catenin signaling has been shown to induce mTOR expression and signaling in intestinal polyps of mutant APC mice, and we have shown that mTOR expression is elevated in uteri of Amhr2-Cre;Ctnnb1Δ(ex3)/+ mice." (PMID 21695255, 2011).
Klinefelter syndrome (1 paper, 2020). A sex chromosome disorder caused by the presence of an extra X chromosome in the male karyotype. "In our tissue sections, AMHR-2 expression is also preserved in testicular pathologies, such as Klinefelter syndrome and Sertoli cell-only syndrome; this is somewhat in contrast with previous reports suggesting that the tubular wall compartment is remodeled in men with impaired spermatogenesis." (PMID 32026338, 2020).
lung adenocarcinoma (1 paper, 2024). A carcinoma that arises from the lung and is characterized by the presence of malignant glandular epithelial cells. "Further studies on the mechanism underlying the reactivation of AMHR2 expression in lung adenocarcinoma are required." (PMID 39230026, 2024). "Owing to the lack of AMHR2‐positive cases in lung squamous cell carcinoma tissues, we investigated the association between AMHR2 immunoreactivity and the clinicopathological features of lung adenocarcinoma cases." (PMID 39230026, 2024). "Given the potential association between AMHR2 expression and lung adenocarcinoma progression, GSEA was performed to determine whether there was a coordinated expression pattern between AMHR2‐related genes and established cell cycle gene sets." (PMID 39230026, 2024). "In the present study, TCGA transcriptomic data of lung adenocarcinoma showed the upregulation of cell cycle‐promoting genes in the AMHR2‐low group." (PMID 39230026, 2024). "An analysis of transcriptomic data from The Cancer Genome Atlas (TCGA) for NSCLC showed that AMHR2 is highly expressed at the mRNA level in 6% of lung adenocarcinomas and 8% of squamous cell carcinomas." (PMID 39230026, 2024). "Comparison of clinicopathological features between AMHR2‐positive and AMHR2‐negative patients with lung adenocarcinoma." (PMID 39230026, 2024). "In lung adenocarcinoma tissues with high expression of AMHR2, activation of the AMH‐AMHR2 pathway may suppress cell proliferation." (PMID 39230026, 2024). "Many questions as to why AMHR2 is expressed in some lung adenocarcinomas remain unanswered." (PMID 39230026, 2024). "We hypothesized that the therapeutic effect of AMH may be applicable to lung adenocarcinomas with high AMHR2 expression." (PMID 39230026, 2024). "Of the 58 lung adenocarcinoma cases tested, 13 (22.4%) were positive for AMHR2." (PMID 39230026, 2024). "In lung adenocarcinoma tissues with high AMHR2 expression, activation of the AMH–AMHR2 pathway may suppress cell proliferation." (PMID 39230026, 2024). "Our data showed that AMHR2 protein expression was detected in 22.4% of lung adenocarcinoma cases and in none of the lung squamous cell carcinoma cases, which is similar to the results of a TCGA transcriptomic analysis for lung adenocarcinoma." (PMID 39230026, 2024).
male infertility (1 paper, 2021). The inability of the male to effect fertilization of an ovum after a specified period of unprotected intercourse. "Other investigations found that activation of β-catenin in Sertoli cells by Amhr2-Cre resulted in male infertility and the loss of germ cells." (PMID 34580275, 2021). "In our present study, we found that the phenotypes in Ppp6ccKO mice are similar to those of previously reported conditional activated allele of the β-catenin in Sertoli cells by using AMH-Cre or Amhr2-Cre by transgenic mouse, including male infertility and the loss of germ cells." (PMID 34580275, 2021).
non-small cell lung carcinoma (1 paper, 2024). A group of at least three distinct histological types of lung cancer, including non-small cell squamous cell carcinoma, adenocarcinoma, and large cell carcinoma. "So far, AMHR2 expression has been confirmed, among others, in non-small cell lung cancer and ocular melanoma." (PMID 39351532, 2024).
ovarian granulosa cell tumor (1 paper, 2011). A granulosa-stromal cell tumor that arises from the ovary. "Since these tumors showed less differentiated morphology and Amhr2-cre is also expressed in granulosa cells at later stages of development, we examined expression of the ovarian granulosa cell tumor markers to rule out the possibility that these tumors might be derived from the granulosa cells." (PMID 21695255, 2011).
prostate carcinoma (1 paper, 2020). A carcinoma that arises from epithelial cells of the prostate gland. "Western blot analysis of lysates from the stably transfected AMHR2-OVCAR8 cell line showed high level detection of AMHR2 protein compared to parental OVCAR8 cells with no detectable AMHR2 in lysates from the human prostate cancer cell line, C4-2." (PMID 32499873, 2020).
serous ovarian carcinoma (1 paper, 2020). "Mice with the genotype Amhr2-Cre Pten(fl/fl) KrasG12D/+(G12D mice) had abnormal follicle structures and developed low-grade serous ovarian carcinomas with 100% penetrance within 18 weeks." (PMID 33244099, 2020). "Because we had generated a low-grade serous ovarian carcinoma mouse model with the Amhr2-Cre Pten(fl/fl) KrasG12D/+ genotype (G12D mice) for a previous study, we decided to generate mice with the Amhr2-Cre Pten(fl/fl) KrasG12V/+ genotype (G12V mice) for the present prospective investigation." (PMID 33244099, 2020).
sterility (1 paper, 2011). "Because Amhr2 is also expressed in mesenchyme-derived tissues in the oviduct and uterus, we examined whether the observed sterility is a phenotypic consequence of conditional knockout of Tgfbr1 in the oviduct and/or uterus." (PMID 22028666, 2011).
testicular tumors (1 paper, 2016). "It is noteworthy that the tumor phenotype was not restricted to females, and males with constitutively active TGFBR1 (i.e., TGFBR1CA Lox/+; Amhr2-Cre) also developed testicular tumors (unpublished data that will be described in an independent report)." (PMID 27344183, 2016).
Turner syndrome (1 paper, 2024). Turner syndrome is a chromosomal disorder associated with the complete or partial absence of an X chromosome. "When attempting to replicate the differentiation process of embryonic granulosa cells, we observed the downregulation of specific genes—GATA4, FOXL2, AMHR2, CYP19A1, and FSH—in Turner syndrome-derived granulosa cells (TS-GCs)." (PMID 39543104, 2024).
type 2 diabetes (1 paper, 2021). "In addition, functional studies may investigate if AMH signalling actually takes place in the pancreas and how this might be related to the pathophysiology of type 2 diabetes, since the receptor through which AMH signals (AMHR2) is expressed in pancreatic tissue." (PMID 33048171, 2021).
varicocele (1 paper, 2020). A condition characterized by the dilated tortuous veins of the spermatic cord with a marked left-sided predominance. "While some studies have reported different patterns of AMH expression in different testicular affections, such as testicular hypotrophy, varicocele, and cryptorchidism, very little is known concerning how AMHR-2 expression is influenced by gonadal pathologies." (PMID 32026338, 2020).
tumor (20 papers, 2011 to 2025). "Other putative tumor suppressor genes include AMHR2, encoding Anti-Mullerian Hormone Receptor Type 2, also known as Mullerian Inhibiting Substance Type II Receptor." (PMID 32537432, 2020). "Not only the targeting of specific antibodies against AMHR2 in tumor tissue should be considered in future oncotherapy, as the anti-proliferative activity of AMH manifests in two aspects the influence on the cell cycle and the regulation of apoptosis." (PMID 39351532, 2024). "The restricted tissue expression combined with the ability to transmit apoptotic signals to cancer cells makes AMHR2 an attractive target for tumor-targeted therapy." (PMID 36979400, 2023). "Our IF and cytometry data also revealed that AMHR2 is expressed by a fraction of tumor cells, especially those that are positive for E-cadherin and CD44, a cancer stem cell marker, in line with previous studies." (PMID 29245952, 2017). "Our data obtained with cultured cells and cells purified from patient ascites demonstrate that macrophages in presence of 3C23K but not with the Fc KO version of this mAb are able to eliminate tumor cells expressing AMHR2." (PMID 29245952, 2017). "At 190 days after transfer of primed splenocytes and tumor inoculation, mean tumor weights were significantly lower in recipients of AMHR2-CD-specific splenocytes compared to recipients of OVA-specific splenocytes (P < 0.05)." (PMID 26618181, 2015). "Tumor growth was significantly inhibited in mice transferred with AMHR2-CD-specific LNCs (P = 0.04) and splenocytes (P < 0.01) when compared to mice receiving OVA-specific LNCs." (PMID 26618181, 2015). "Even though pretumoral lesions were present in the ovaries of all young Amhr2-Cre;Ctnnb1Δ(ex3)/+ mice, advanced tumor development only occurred in approximately 50% of mice by the age of 8-month to 1-year." (PMID 21695255, 2011). "Tumor cells were collected from Amhr2-Cre;Ctnnb1Δ(ex3)/+;PtenΔ/Δ mutant ovaries and injected into the dorsal flanks of 10 NOD/SCID mice in order control for uniformity at the start of the experiment." (PMID 21695255, 2011). "In the tumor microenvironment, a low fucosylated antibody against AMHR2, murlentamab (GM102), switches the pro-cancer nature of tumor-associated macrophages (TAMs) towards the anti-cancer action by activating immunological mechanisms leading to the destruction of tumor cells." (PMID 39351532, 2024). "AMHR2-CD vaccination significantly inhibited ID8 tumor growth when administered either prophylactically or therapeutically, and protection against EOC growth was passively transferred into naive recipients with AMHR2-CD-primed CD4+ T cells but not with primed B cells." (PMID 26618181, 2015). "In addition, AMHR2-CD vaccination resulted in a significantly decreased overall tumor load as measured by final ID8 tumor weight at termination of experiments in mice vaccinated 7 days (P < 0.01) and 1 day (P < 0.05) prior to ID8 inoculation." (PMID 26618181, 2015). "We have observed early onset of tumor development in Amhr2-Cre;Ctnnb1Δ(ex3)/+;PtenΔ/Δ mice." (PMID 21695255, 2011). "To examine whether PTEN deletion could affect tumor progression in Amhr2-Cre;Ctnnb1Δ(ex3)/+ ovaries, we developed another mouse model by deleting exon 3 of the β-catenin in PTEN negative cells of the mouse ovary (Amhr2-Cre;Ctnnb1Δ(ex3)/+;PtenΔ/Δ)." (PMID 21695255, 2011).
tumor (continued). "Since Amhr2-Cre is also expressed in the ovarian surface epithelium, immunofluorescence was performed using antibodies against epithelial cell markers, cytokeratin 8 (KRT8) and 17/19 (KRT17/19), to exclude the epithelial cell identity of the neoplasms." (PMID 27344183, 2016). "It is notable that a single immunization with AMHR2-CD is capable of inducing sufficient tumor immunity without eliciting a detectable CD8 T cell response." (PMID 26618181, 2015). "However, tumor progression has up to a year long latency period in Amhr2-Cre;Ctnnb1Δ(ex3)/+ mice and no change was observed in the mortality rate of these animals, even though the pretumoral lesions were present in 4-week old ovaries." (PMID 21695255, 2011). "AMHR2-CAR-T cells also recognized a number of human ovarian and endometrial cancer cell lines and lysed a number of patient tumor samples in vitro without killing normal human cells." (PMID 36979400, 2023).
cancer (12 papers, 2010 to 2024). A tumor composed of atypical neoplastic, often pleomorphic cells that invade other tissues. "Better response to treatment increased and was associated with a higher number of cancer cells with AMHR2 expression." (PMID 39351532, 2024). "This suggests that the AMHR2‐high group exhibited cell cycle suppression, indicating slower cancer progression." (PMID 39230026, 2024). "Under the same conditions, surgically resected cancer specimens from 79 patients with NSCLC were stained with anti‐AMHR2 antibody." (PMID 39230026, 2024). "The presence of AMHR2 in the tissue is a crucial aspect of the modern approach to targeted oncological therapy using the anti-cancer properties of AMH." (PMID 39351532, 2024). "For example, antibodies targeting AMHR2 are being investigated for their potential in diagnosing and treating various cancers." (PMID 39351532, 2024). "Thus, it may be advisable to combine the treatment of specific cancers (expressing AMHR2 and microsatellite instability) with these two agents." (PMID 39351532, 2024). "A recent screening for AMHR2 protein expression using a panel of 631 samples from 15 different nongynecological cancers (including 18 NSCLC cases) revealed that AMHR2 is expressed in various solid tumors." (PMID 39230026, 2024). "The aim of this narrative review is to systematize knowledge about the expression of AMH and AMHR2 in various tissues, in order to gather information on the mechanism of action of AMH in physiological and various medical conditions, especially concerning malignant tumors." (PMID 39351532, 2024). "In addition, one must evaluate the significance of species-specific differences in tissue expression of cancer vaccine targets, since, unlike the mouse, AMHR2 transcripts have not been detected in any of the normal human brain tissues examined." (PMID 26618181, 2015). "Taken together, these findings demonstrate the potential of the AMH‐AMHR2 pathway as a candidate for molecular targeted therapy; however, simply administering AMH to cancers with high AMHR2 expression may not necessarily be appropriate." (PMID 39230026, 2024).
gynecologic tumor (1 paper, 2020). "Using Cre recombinase driven by the promoter of Amhr2, we generated mice with the genotype Ptenfl/fl KrasG12D/+ Amhr2-Cre (G12D mice) or with Ptenfl/fl KrasG12V/+ Amhr2-Cre (G12V mice), in which different types of gynecologic tumors developed." (PMID 33244099, 2020).
AMHR2 also shares sentences with these, for which no sentence is quoted: Mayer-Rokitansky-Küster-Hauser syndrome (2 papers); adenomyosis (1); adrenocortical carcinoma (1); Autoimmunity (1); Azoospermia (1); basal cell carcinoma (1); cervical cancer (1); clear cell ovarian carcinoma (1); cutaneous melanoma (1); fallopian tube carcinoma (1); hepatocellular carcinoma (1); Hodgkins lymphoma (1); hydrocele (1); Hypertension (1); hypogonadotrophic hypogonadism (1); hypoparathyroidism (1); infection (1); leiomyoma (1); lung squamous cell carcinoma (1); lymph node metastasis (1); malignant pleural mesothelioma (1); Miscarriage (1); mullerian aplasia (1); non-Hodgkin lymphoma (1); Obesity (1); oligospermia (1); ovarian carcinosarcoma (1); ovarian dysgerminomas (1); ovarian endometriosis (1); pheochromocytoma (1).
A further 10 diseases each share a sentence with AMHR2 in 1 paper.